TKTL2 (transketolase like 2)
Description:
Plays an essential role in total transketolase activity and cell proliferation in cancer cells; after transfection with anti-TKTL1 siRNA, total transketolase activity dramatically decreases and proliferation was significantly inhibited in cancer cells. Plays a pivotal role in carcinogenesis.
Synonyms: FLJ32975; DKFZP434L1717
Tractability: PROTAC: ubiquitination databases record sites on it.
Gene: Protein-coding gene on chromosome 4 (163,471,095 to 163,473,754, reverse strand). Ensembl gene ENSG00000151005.
Gene Ontology:
Molecular function: thiamine pyrophosphate binding; transketolase activity
Cellular component: cytoplasm; cytosol
Genetic constraint (gnomAD): Loss-of-function variants: 0 observed, 1.34 expected, observed/expected ratio (o/e) 0, 90% interval 0 to 1.61. That is too few expected variants to judge how well the gene tolerates losing a copy. Missense variants: 825 observed, 837.69 expected, observed/expected ratio (o/e) 0.98, 90% interval 0.93 to 1.04. Synonymous variants: 259 observed, 308.88 expected, observed/expected ratio (o/e) 0.84, 90% interval 0.76 to 0.93.
Homologues: Orthologues: chimpanzee TKTL2 (99% identical), macaque TKTL2 (96% identical), rat Tktl2 (81% identical), mouse Tktl2 (81% identical), guinea pig TKTL2 (79% identical), pig TKTL2 (74% identical), tropical clawed frog tktl2 (72% identical), zebrafish tktb (69% identical), rabbit TKTL2 (65% identical). Paralogues in human: TKTL1 (70% identical), TKT (66% identical), BCKDHB (15% identical), PDHB (15% identical).
Diseases named in the same sentence as TKTL2 in open-access papers:
TKTL2 is named in the same sentence as 8 diseases in open-access papers, as found by Europe PMC text mining. Sharing a sentence is not in itself a finding about the gene and the disease. The quoted sentences say what the papers report.
cervical cancer (2 papers, 2009 to 2019). A primary or metastatic malignant neoplasm involving the cervix. "When human cervical cancer HeLa cells were synchronized to G1/S phase by double thymidine, endogenous levels of TKTL1, but not TKT and TKTL2, increased." (PMID 31175280, 2019).
colon carcinoma (2 papers, 2006 to 2011). "In contrast, the TKTL2 transcript was downregulated more than 10-fold in three out of five colon carcinomas." (PMID 16465194, 2006). "Similar to its downregulation in colon carcinomas, TKTL2 expression was downregulated more than 10-fold in two of five lung adenocarcinomas." (PMID 16465194, 2006). "TKTL1 expression in colon cancer was shown to be upregulated as compared to TKT and TKTL2 expression using immunohistochemistry and cell culture assays." (PMID 21854597, 2011).
diabetes (2 papers, 2019 to 2022). "Together these results support our hypothesis that TKTL1 and TKTL2 are functional transketolases and thus opens up the possibility that altered activity/function may be implicated in diseases such as diabetes and cancer." (PMID 30646877, 2019). "Some researchers have suggested TKTL1 and TKTL2 are functional transketolases and represent novel therapeutic targets for diabetes and cancer 20, 45-47." (PMID 35711845, 2022). "Our data support the hypothesis that TKTL1 and TKTL2 are functional transketolases and represent novel therapeutic targets for diabetes and cancer." (PMID 30646877, 2019).
leukemia (1 paper, 2022). A malignant (clonal) hematologic disorder, involving hematopoietic stem cells and characterized by the presence of primitive or atypical myeloid or lymphoid cells in the bone marrow and the blood. "These genes are LYZL6 in BC tissues and SCP2D1 and TKTL2 genes in the majority of leukemia tissues." (PMID 35627192, 2022). "TKTL2 expression was also observed in 50% of leukemia samples but not in the BC samples." (PMID 35627192, 2022).
cancer (4 papers, 2006 to 2025). A tumor composed of atypical neoplastic, often pleomorphic cells that invade other tissues. "Being an enzyme that is important for cell biosynthesis, TKT, as well as both the TKTL1 and TKTL2 isoenzymes, have turned out to be important prognostic markers and potential regulatory targets in various cancer types." (PMID 41302487, 2025). "The expression of TKT (P < 0.001) and TKTL2 (P < 0.05) mRNA were dramatically higher in cancer than the normal tissues." (PMID 35711845, 2022).
tumor (2 papers, 2006 to 2023). "So far, three human transketolase genes have been recognised, and the relative contributions of TKT, transketolase-like-1 (TKTL1), and transketolase-like-2 (TKTL2) to tumour-specific transketolase metabolism have not been investigated." (PMID 16465194, 2006). "The enzymatic properties of TKTL1, its upregulation in tumours, and the absence of upregulation of TKT and TKTL2 indicate that TKTL1 is the transketolase targeted by anti-transketolase drugs." (PMID 16465194, 2006). "Here, we provide evidence that TKTL1 mRNA and protein are specifically overexpressed in tumours, whereas TKT and TKTL2 expression are not upregulated." (PMID 16465194, 2006).
TKTL2 also shares sentences with these, for which no sentence is quoted: lung adenocarcinoma (1 paper); ovarian carcinoma (1).